CAPN1 (calpain 1)
Diseases named in the same sentence as CAPN1 in open-access papers (continued):
Sharing a sentence is not in itself a finding about the gene and the disease.
Hepatic steatosis (1 paper, 2025). Steatosis is a term used to denote lipid accumulation within hepatocytes. "We showed that eight weeks of sucrose intake induces liver steatosis and fibrosis, which was associated with impaired CAPN1 activity and increases levels of PPARγ protein." (PMID 41468440, 2025). "Future works in mice models deficient of CAPN1 could demonstrate whether deficiency in this protease increases the susceptibility of developing liver steatosis induced by sucrose, as well as the involved downstream mechanisms." (PMID 41468440, 2025). "To explore the possible mechanism by which calpain inhibition promotes hepatic steatosis, we evaluated the protein abundance of PPARγ, which is cleaved by CAPN1 in cell-free systems and promotes de novo lipogenesis in MASLD." (PMID 41468440, 2025). "Liver steatosis induced by S and A + S correlated with decreased calpain-1 protein abundance and calpain-dependent αII-spectrin proteolysis." (PMID 41468440, 2025). "Since no reports associate the development of hepatic steatosis with a decrease in calpain activity and CAPN1 protein abundance, we performed a prove of concept experiment in the human hepatocarcinoma cell line model (HepG2)." (PMID 41468440, 2025). "Thus, autophagy dysregulation could be an alternative mechanism linking CAPN1 inhibition and hepatic steatosis, which could be insensitive to arsenic." (PMID 41468440, 2025). "In contrast, eight weeks of arsenic exposure did not induce liver steatosis, and although it decreased CAPN1 protein levels, this exposure did not affect its proteolytic activity and PPARγ levels." (PMID 41468440, 2025).
hepatoma (1 paper, 2017). "The results confirm that calpain-1 is overexpressed and calpastatin is reduced in the muscle of rats implanted with the AH-130 hepatoma, and show for the first time that the Ca2+-dependent proteolytic system is overactivated also in the C26-bearing mice." (PMID 28469577, 2017).
hereditary ataxia (1 paper, 2016). An instance of an atactic disorder that is caused by an inherited genomic modification in an individual. "In agreement with a previous study, one histopathologically confirmed case of hereditary ataxia and two clinically affected cases carried neither the CAPN1:c.344G > A allele nor the homozygous KCNJ10:c.627C > G genotype." (PMID 27724896, 2016). "Genetic testing using the KCNJ10:c.627C > G and the CAPN1:c.344G > A mutations deems not to be sufficient to capture all cases of hereditary ataxia in PRT and JRT." (PMID 27724896, 2016). "However, some cases of hereditary ataxia could not be explained through the KCNJ10:c.627C > G nor the CAPN1:c.344G > A mutation." (PMID 27724896, 2016).
hereditary cardiomyopathies (1 paper, 2024). "CAPN1 had heart enhanced interactions with ACTC1 and ACTN2, which participate in the formation of the actin cytoskeleton and are previously associated with hereditary cardiomyopathies." (PMID 38848015, 2024).
Hypercholesterolemia (1 paper, 2015). An increased concentration of cholesterol in the blood. "The results suggested that calpain-1 activation mediates the vascular calcification induced by hypercholesterolemia or oxLDL." (PMID 26047104, 2015). "The present study showed that CAI, the specific calpain inhibitor, inhibited the vascular calcification in rats with hypercholesterolemia and that siRNA against calpain-1 reduced the calcium deposition in RVSMCs treated with oxLDL." (PMID 26047104, 2015). "The present study suggested that calpain-1 mediates the calcium deposition in aortic tissue of rats with hypercholesterolemia and RVSMCs treated with oxLDL based on the following findings." (PMID 26047104, 2015).
Hyperglycemia (1 paper, 2022). An increased concentration of glucose in the blood. "Besides, hyperglycemia induces the calpain-1 expression in the mitochondria and cleaves the ATP synthase α subunit, resulting in reduced ATP synthase activity." (PMID 35389830, 2022).
hyperhomocysteinemia (1 paper, 2014). A serious metabolic condition caused by mutations in the MTHFR gene, medications, or nutritional deficiency. "Study has shown that hyperhomocysteinemia induces the translocation of active calpain-1 from cytosol to mitochondria, leading to increased intramitochondrial oxidative stress in cultured rat heart microvascular endothelial cells." (PMID 24886224, 2014).
hypertrophic cardiomyopathy (1 paper, 2010). A condition in which the myocardium is hypertrophied without an obvious cause. "Gene expression profiling of hypertrophic cardiomyopathy revealed the overexpression of various cytoskeletal proteins including β-actin, α−actin, tropomyosin, fibronectin, calpain-1, and β-myosin heavy chain." (PMID 20635003, 2010).
hyperuricemia (1 paper, 2024). An abnormally high level of uric acid. "Hyperuricemia also inhibits myocardial cells activity by activating the extracellular signal-regulated kinase pathway and induces cardiomyocyte apoptosis by activating calpain-1, thus leading to damage to the myocardium." (PMID 39796029, 2024).
inflammatory breast carcinoma (1 paper, 2016). An advanced, invasive breast adenocarcinoma characterized by the presence of distinct changes in the overlying skin. "Low calpain-1 expression was associated with adverse survival in inflammatory breast cancer cases (P=0.003) and low calpain-2 was associated with adverse survival in the non-inflammatory breast cancer cases (P=0.031)." (PMID 27323818, 2016). "In addition, low calpain-2 expression was associated with adverse survival in non-inflammatory breast cancer patients and low calpain-1 expression was associated with adverse survival in inflammatory breast cancer patients." (PMID 27323818, 2016).
intestinal infection (1 paper, 2022). "Taken together, the results of our study revealed calpain-1 to be a novel antiviral protein in porcine small intestinal mucus, suggesting that calpain-1 has potential for defending against intestinal infections." (PMID 36102516, 2022).
invasive breast carcinoma (1 paper, 2016). A carcinoma that infiltrates the breast parenchyma. "In early invasive breast cancer expression of calpain-1, calpain-2 and their inhibitor, calpastatin, have been associated with clinical outcome and clinicopathological factors." (PMID 27323818, 2016).
laryngeal carcinoma (1 paper, 2020). Carcinoma that arises from the laryngeal epithelium. "Clinical studies have shown that the expression of CAPN1 is positively related to tumor volume, invasion, distant metastasis and poor prognosis in patients with laryngeal cancer." (PMID 32395869, 2020).
Lewy body diseases (1 paper, 2014). "Although these data may predict a role for reduced CAPN1-mediated cleavage of α-syn in the pathogenesis of Lewy body diseases, some questions remain." (PMID 25476568, 2014).
limb-girdle muscular dystrophy (1 paper, 2023). Limb-girdle muscular dystrophy (LGMD) is a heterogeneous group of muscular dystrophies characterized by proximal weakness affecting the pelvic and shoulder girdles. "Humans have three clp-4 orthologs, CAPN1 (calpain 1), CAPN2 (calpain 2) and CAPN3 (calpain 3), which have been implicated in limb-girdle muscular dystrophy." (PMID 37628820, 2023).
Lissencephaly (1 paper, 2017). A spectrum of malformations of cortical development caused by insufficient neuronal migration that subsumes the terms agyria, pachygyria and subcortical band heterotopia. "Calpain 1/2 inhibitors, ALLNal and SNJ1945 are therapeutically beneficial in LIS1-related lissencephaly." (PMID 29245980, 2017).
liver inflammation (1 paper, 2025). "Moreover, CAPN1 (gene for calpain-1) KO has protected high-fat-diet (HFD)-fed mice from developing liver inflammation, as indicated by decreased levels of oxidized low-density lipoprotein (oxLDL), malondialdehyde (MDA), TNF-α, and IL-6." (PMID 41294867, 2025).
nephrotic syndrome (1 paper, 2023). A collection of symptoms that include severe edema, proteinuria, and hypoalbuminemia; it is indicative of renal dysfunction. "Interestingly, more recent reports show that TRPC6 activity is linked to increased calpain 1 and calcineurin activity contributing to PAN-induced podocyte injury as well as promoting the pathogenesis of nephrotic syndrome and podocyte injury." (PMID 37615749, 2023).
neurogenic muscle atrophy (1 paper, 2022). "A direct role for calpain-1 has been demonstrated for desmin filament disassembling in neurogenic muscle atrophy, since calpain-1 down-regulation prevents desmin loss, myofibril destruction and muscle atrophy." (PMID 36422289, 2022).
non-alcoholic steatohepatitis (1 paper, 2025). "Also, the protein levels of CAPN1 increased in the livers from non-alcoholic steatohepatitis patients." (PMID 41468440, 2025).
oesophageal cancer (1 paper, 2024). "Furthermore, in oesophageal cancer cells cis-platin targets calpain-1 (CAPN1) and calpain-2 (CAPN2)." (PMID 39097717, 2024).
perinatal asphyxia (1 paper, 2020). A disorder caused by a lack of blood flow or gas exchange to or from the fetus in the period immediately before, during, or after the birth process. "In addition, DIM inhibited apoptosis and oxidative stress accompanying perinatal asphyxia through: downregulation of FAS, CASP-3, CAPN1, GPx3 and SOD-1, attenuation of caspase-9 activity, and upregulation of anti-apoptotic Bcl2 mRNA." (PMID 32816128, 2020).
platelet disorders (1 paper, 2013). "Conversely, there have been no suggestions of platelet disorders in dogs homozygous for the CAPN1 variant, although this potential defect has not been formally investigated." (PMID 23741357, 2013).
prostate carcinoma (1 paper, 2017). A carcinoma that arises from epithelial cells of the prostate gland. "The results indicate that calpains, most likely calpain 1, play a critical role in Cao2+-induced filamin A cleavage, which leads to a remodeling of actin cytoskeleton and an increase in the migration of AR-deficient prostate cancer cells." (PMID 27206800, 2017).
renal cell carcinoma (1 paper, 2017). "Calpain-1 was also found to be associated with lymph node status in other types of cancer, such as renal cell carcinoma." (PMID 28536704, 2017).
sarcoidosis (1 paper, 2025). Sarcoidosis is a multisystemic disorder of unknown cause characterized by the formation of immune granulomas in involved organs. "As depicted on the volcano plot, the most downregulated protein in sarcoidosis was calpain-1 catalytic subunit (P07384, log2FC, −4.9 and log10P, 14.9), followed by acyl-CoA-binding domain-containing protein 6 (Q9BR61, log2FC, −3.6 and log10P, 6.5)." (PMID 41279897, 2025).
schistosomiasis (1 paper, 2019). An infectious disease caused by parasitic trematodes of the genus Schistosoma that colonize human blood vessels and release eggs that can cause granulomatous reactions leading to acute (swimmer's itch or acute schistosomiasis syndrome) or chronic disease. "SmeCalp1 was found to be closely related to calpain 1 of S. mansoni (SmCalp1.3) and S. japonicum (Sj-CCalp1), which have also been recently investigated for potential vaccine development against schistosomiasis." (PMID 31362766, 2019). "Moreover, the cross-reaction among these species might imply that calpain 1 could be used as a target for development of a pan-vaccine or pan-chemotherapeutic agent for prevention of broad schistosomiasis in humans or animals." (PMID 31362766, 2019).
SMA type 4 (1 paper, 2021). "In this work we identified CAPN1 as a new genetic cause for SMA type 4." (PMID 35126465, 2021).
status epilepticus (1 paper, 2025). Status epilepticus is defined as a continuous seizure lasting more than 30 min, or two or more seizures without full recovery of consciousness between any of them. "In the hippocampus of pilocarpine-induced status epilepticus (PISE) mice, the ratio of inactive calpain 1 protein level to its total protein level (inactive/total calpain 1) significantly decreased, while the ratio of inactive calpain 2 protein level to its total protein level remained unchanged." (PMID 40205503, 2025).
steatosis (1 paper, 2025). Increased lipid within the cytoplasm of cells. "Interestingly, co-administration of A + S induced steatosis, displayed lower fibrosis levels than sucrose alone, diminished CAPN1 levels but displayed attenuated inhibition of calpain proteolytic activity and did not have increased PPARγ levels." (PMID 41468440, 2025). "A-treated rats did not develop steatosis, displayed decreased calpain-1 levels but its proteolytic activity remained intact." (PMID 41468440, 2025).
thoracic aortic aneurysm (1 paper, 2018). An aneurysm formed in the wall of the proximal portion of the descending aorta proceeding from the arch of the aorta. "In the aorta, aggrecan degradation is likely to be due to increase in the activity and expression of aortic MMP-2, MMP-9 and Calpain-1 with advancing age33–37, whilst increased ADAMTS levels promote thoracic aortic aneurysm progression." (PMID 29867203, 2018).
thrombosis (1 paper, 2019). "Also, the impaired arterial thrombosis reported for Capn1−/− mice did not match with a measured higher platelet adhesion under flow, although it should be noted that the latter mice showed a complex pattern of increased and decreased platelet activation parameters in vitro." (PMID 31417909, 2019).
uterine corpus endometrial carcinoma (1 paper, 2025). A endometrial carcinoma (disease) that involves the body of uterus. "This study focuses on the interaction of wild-type and mutant β-integrins with calpain-1 and 2 in uterine corpus endometrial carcinoma (UCEC)." (PMID 40362482, 2025).
tumor (29 papers, 2012 to 2025). "In pancreatic cancer, which is notorious for rapid metastatic spread, high tumor calpain-1 expression is associated with increased metastasis and shorter overall survival." (PMID 40940726, 2025). "The risk heatmap clearly showed CAPN1 was down-regulated in high-risk group, implying a tumor-suppressor role." (PMID 32998713, 2020). "With low calpain-1 expression associating with stage 1 tumour, in the current study, low Syk-c and MAP4 expression also related to organ-confined status (Syk-c: χ2 = 9.975, df = 1, P = 0.002; and MAP4: χ2 = 15.402, df = 1, P = 0.000087)." (PMID 30737623, 2019). "Several studies later it was shown that calpain-1 expression was significantly associated with tumor grade, proliferation, and apoptosis." (PMID 28536704, 2017). "High expression of calpastatin was associated with ER positive tumours (χ2=5.720, d.f.=1, P=0.017) and high calpain-1 expression was associated with PgR positive tumours (χ2=5.457, d.f.=1, P=0.019)." (PMID 27323818, 2016). "In addition to the association with survival of these patients, high calpastatin expression is associated with ER positive tumours and high calpain-1 expression is associated with PgR positive tumours." (PMID 27323818, 2016). "In addition, calpain-1 expression showed significant association with tumour stage suggesting that calpain-1 might mediate tumour spread." (PMID 30737623, 2019). "Considering the elevation in intracellular calcium levels under hypoxic conditions and in the inner region of tumor spheroids, hypoxia can activate both calpain 1 and 2, the major isoforms of calpain." (PMID 40151834, 2025). "After ultrasound treatment, calpain 1 and 2 knockdown cells had remarkably low levels of apoptosis compared to the ultrasound‐treated tumor cells, indicating that calpain played a significant role in mechanoptosis." (PMID 40060768, 2025). "In OC, BRCA1 affects the migration of tumor cells by regulating CAPN1 and plays an important role in double-stranded DNA damage repair via its interaction with SIRT2." (PMID 35941978, 2022). "In tumor tissues, CAPN1 expression was significantly lower in CT + TT than in CC genotype (P = 0.01)." (PMID 34728688, 2021). "Quantitative RT-PCR showed that the relative CAPN1 expression was significantly higher in tumor tissue than in normal lung tissue (P = 0.003)." (PMID 34728688, 2021). "Both CM presented proteins involved in proliferation of both tumor and non-tumor cells, of which CAPN1, CST1, LAMC2 and RANBP3 stood out in CM3D and GPC6, ILK, MAPK1, MIF and PICALM in CM2D." (PMID 34884877, 2021). "How MAP4, Syk and calpain-1 are involved in tumour cell spreading/migration, and in cellular response to taxane-containing chemotherapy, remains to be elucidated." (PMID 30737623, 2019). "Calpain-1 and calpain-2 demonstrated cytoplasmic staining with some granularity and heterogeneity between adjacent tumour cells, varying from weak to intense staining with a few instances of calpain-2 nuclear staining." (PMID 23140395, 2012). "Calpain-1/2 isoforms contribute to tumor cell migration, invasion, and metastasis by limited proteolysis of intracellular protein substrates, including those which contribute to the regulation of focal adhesion dynamics and promotion of cytoskeletal remodeling." (PMID 40940726, 2025). "Interestingly, it has been demonstrated that cathepsin B and calpain-1, both enzymes able to cleave HO-1, are overexpressed in this type of tumor and such expression has been identified as an independent unfavorable prognostic factor." (PMID 33440611, 2021). "Interestingly, low calpain-1 expression was more frequent in patients with confined tumours (stage 1) (χ2 = 11.310, df = 1, P = 0.001)." (PMID 30448882, 2019). "Overall, the current results suggest that Syk, MAP4, and calpain-1 expression are correlated with each other and these proteins may be involved in early stages of tumour spread." (PMID 30737623, 2019).